D2HGDH (D-2-hydroxyglutarate dehydrogenase)
Description:
Catalyzes the oxidation of D-2-hydroxyglutarate (D-2-HG) to alpha-ketoglutarate. Also catalyzes the oxidation of other D-2-hydroxyacids, such as D-malate (D-MAL) and D-lactate (D-LAC). Exhibits high activities towards D-2-HG and D-MAL but a very weak activity towards D-LAC.
Synonyms: D2HGD; MGC25181; FLJ42195
Tractability: Small molecule: a structure with a bound ligand is known. PROTAC: ubiquitination databases record sites on it; its protein half-life has been measured.
Gene: Protein-coding gene on chromosome 2 (241,734,596 to 241,768,816, forward strand). Ensembl gene ENSG00000180902.
Subcellular location: Mitochondrion
Subcellular location (Human Protein Atlas): Mitochondria
Pathways (Reactome):
Metabolism: Interconversion of 2-oxoglutarate and 2-hydroxyglutarate
Gene Ontology:
Molecular function: (R)-2-hydroxyglutarate dehydrogenase activity; zinc ion binding; catalytic activity; FAD binding; flavin adenine dinucleotide binding
Biological process: malate metabolic process; protein destabilization; 2-oxoglutarate metabolic process; lactate metabolic process; response to calcium ion; response to cobalt ion; response to magnesium ion; response to manganese ion; response to zinc ion; tartrate metabolic process
Cellular component: mitochondrion; mitochondrial matrix
Genetic constraint (gnomAD): Loss-of-function variants: 29 observed, 43.49 expected, observed/expected ratio (o/e) 0.67, 90% interval 0.5 to 0.91. The upper end of that interval is the gene's LOEUF score, 0.91, which puts it in group 3 of 6, group 1 being the genes least tolerant of losing a copy. Missense variants: 612 observed, 648.68 expected, observed/expected ratio (o/e) 0.94, 90% interval 0.88 to 1.01. Synonymous variants: 316 observed, 295.11 expected, observed/expected ratio (o/e) 1.07, 90% interval 0.98 to 1.17.
Gene-disease validity (ClinGen):
ClinGen rates the evidence that D2HGDH causes each of these diseases.
mitochondrial disease (autosomal recessive): Definitive.
Homologues: Orthologues: chimpanzee D2HGDH (99% identical), macaque D2HGDH (83% identical), rabbit D2HGDH (83% identical), dog D2HGDH (81% identical), rat D2hgdh (81% identical), mouse D2hgdh (81% identical), guinea pig D2HGDH (79% identical), pig D2HGDH (73% identical), tropical clawed frog d2hgdh (63% identical), zebrafish d2hgdh (62% identical), Drosophila melanogaster D2hgdh (47% identical), Caenorhabditis elegans dhgd-1 (41% identical). Paralogues in human: LDHD (26% identical), AGPS (22% identical).
Diseases named in the same sentence as D2HGDH in open-access papers:
D2HGDH is named in the same sentence as 40 diseases in open-access papers, as found by Europe PMC text mining. Sharing a sentence is not in itself a finding about the gene and the disease. The quoted sentences say what the papers report.
glioma (7 papers, 2020 to 2025). A benign or malignant brain and spinal cord tumor that arises from glial cells (astrocytes, oligodendrocytes, ependymal cells). "The paucity of evidence linking D2hgdh mutations with glioma occurrence is striking considering the wide-spread prevalence of IDH1/IDH2 mutations in these tumors." (PMID 40236175, 2025). "FAIM showed overlap between gene expression and alternative splicing (cerebellum in all glioma, P = 6.93 × 10−5) and D2HGDH showed overlap between protein abundance and gene expression (cortex in all glioma, P = 8.70 × 10−5)." (PMID 39565278, 2025). "While it is already known that the CCDC26 is a causal variant for IDHmut glioma, these findings highlight the importance of prioritizing the PHLDB1 and D2HGDH regions in future functional experiments." (PMID 40709013, 2025). "To understand the development of adult glioma, we demonstrate that D2HGDH and PHLDB1 should be prioritized for functional studies in IDHmut tumors." (PMID 40709013, 2025). "All variants were in two known glioma regions: 11 variants in PHLDB1 (most significant rs7125115, meta P = 1.73 × 10−13, Mayo GWAS OR = 1.48) and 10 variants in D2HGDH (most significant rs71430382, meta P = 8.86 × 10−10, Mayo GWAS OR = 1.65)." (PMID 40709013, 2025). "While there is overwhelming evidence that D-2HG acts as an oncometabolite in cells that express mutant IDH1/IDH2, there is limited evidence indicating that changes in D2hgdh expression or activity drive glioma progression, with only a handful of studies hinting this possibility." (PMID 40236175, 2025). "Specifically, among adult glioma patients that do not carry a risk allele (G-allele) for rs55705857, the D2HGDH and PHLDB1 variants increased the likelihood of having a tumor that is IDHmut." (PMID 40709013, 2025). "D2HGDH is a marker of colorectal cancer, glioma, and prostate cancer." (PMID 31927533, 2020). "Therefore, increased D2HGDH protein abundance may be protective against glioma by preventing the accumulation of D-2-HG, via catalytic conversion of D-2-HG to 2-OG." (PMID 39565278, 2025). "We searched for differential gene expression of HBEGF and D2HGDH in non-tumour and glioma samples from the Rembrandt and TCGA studies, using the GlioVis tool." (PMID 39565278, 2025). "Additionally, we identified five genes that not been implicated in glioma previously: CEP192 (18p11.21), D2HGDH (2q37.3) FAIM (3q22.3), HBEGF (5q13.3) and SLC8A1 (2p22.1)." (PMID 39565278, 2025). "There were significant differences in D2HGDH expression between non-tumour samples (controls) and all glioma subtypes (GB (P = 1.30 × 10−6), astrocytoma (P = 9.00 × 10−7), oligodendroglioma (P = 1.50 × 10−7), mixed glioma (P = 9.40 × 10−3) or unknown histology (P = 2.50 × 10−9))." (PMID 39565278, 2025).
asthma (6 papers, 2018 to 2026). "D2HGDH variant rs71430382 was associated with immune system related traits such as eosinophil cell count, asthma, eczema, anaphylaxis and respiratory disease." (PMID 39565278, 2025). "Notable examples include D2HGDH in lung tissue for asthma, CYBRD1 in breast mammary tissue for breast cancer, and CCR6 in spleen tissue for rheumatoid arthritis." (PMID 42201988, 2026). "The D2HGDH PTV is in partial LD with an intronic variant rs34290285 in D2HGDH (r2 = 0.366, LDlink) that has been associated with asthma and allergic disease in the initial UK Biobank data release." (PMID 29691392, 2018).
colorectal cancer (4 papers, 2016 to 2021). A primary or metastatic malignant neoplasm that affects the colon or rectum. "Notably, D-2hydroxyglutarate dehydrogenase (D2HGDH), which was upregulated in subtype 3, was observed to drive progression to colorectal cancer during colitis." (PMID 34603397, 2021). "D2HGDH transcriptional regulation studies in colorectal cancer have recently been reported." (PMID 30908763, 2019). "We therefore examined for mutations of D2HGDH, and its counterpart for L-2HG, L-2HG dehydrogenase in DLD1, HCT116 and RKO cells through sequencing, and found both enzymes to be wild-type in the three colorectal cancer cell lines." (PMID 27824159, 2016).
breast carcinoma (3 papers, 2022 to 2026). "Our study reveals a significant elevation of D-2HG levels in the serum and tumor tissues of TNBC, potentially regulated by high PHGDH expression and low D2HGDH expression, both of which correlate with poor prognosis in breast cancer." (PMID 39910592, 2025). "As one of α-ketoglutarate-dependent dioxygenases, ALKBH7 expression was positively associated with D-2-hydroxyglutarate dehydrogenase(D2HGDH) as Gene expression profile data and later is considered a potential prognostic marker in breast cancer." (PMID 35980268, 2022). "Moreover, Kaplan–Meier plotter database analysis suggested that high PHGDH expression and low D2HGDH expression are both strongly connected with a poor outcome for breast cancer." (PMID 39910592, 2025). "Comparable results were noted in cell lines of breast cancer, indicating D-2HG accumulation was prominently regulated by PHGDH and D2HGDH in TNBC." (PMID 39910592, 2025). "The qPCR analysis of PHGDH and D2HGDH expression in tissue samples, along with TCGA database analysis, revealed that PHGDH expression was highest and D2HGDH expression was lowest in TNBC tumors compared to other breast cancer subtypes." (PMID 39910592, 2025).
angiokeratoma (2 papers, 2025). A vascular lesion in the papillary dermis resulting from ectasia of pre-existing vessels. "D2hgdh mutations in humans lead to developmental delays and as well as hypermelanization of the abdominal region – a condition termed angiokeratoma, which is characterized by benign skin lesions." (PMID 40236175, 2025).
brain tumors (2 papers, 2016 to 2025). "The high concentrations of D2HG produced in mIDH1 brain tumors overcome detoxification by d-2-hydroxyglutarate dehydrogenase (D2HGDH), and thus, other avenues to minimize D2HG are avidly being pursued." (PMID 27781195, 2016).
developmental delays (2 papers, 2025). "For example, loss-of-function mutations in the human D2hgdh gene result in an inborn error of metabolism known as D-2-hydroxyglutaric aciduria, which is characterized by elevated urinary D-2HG levels, developmental delays, seizures, and brain abnormalities." (PMID 40236175, 2025).
diffuse large B-cell lymphoma (2 papers, 2015 to 2021). "Conversely, the D2HGDH mutants that we find in diffuse large B-cell lymphoma are enzymatically inert." (PMID 26178471, 2015). "D-2-hydroxyglutarate dehydrogenase (D-2-HGDH) catalyzes the oxidation of D-2-hydroxyglutarate (D-2-HG) into 2-oxoglutarate, and genetic D-2-HGDH deficiency leads to abnormal accumulation of D-2-HG which causes type I D-2-hydroxyglutaric aciduria and is associated with diffuse large B-cell lymphoma." (PMID 33431826, 2021).
epilepsy (2 papers, 2020 to 2025). A brain disorder characterized by episodes of abnormally increased neuronal discharge resulting in transient episodes of sensory or motor neurological dysfunction, or psychic dysfunction. "Because D2HGDH is strongly linked to epilepsy, we used human brain tissue from patients with temporal lobe epilepsy (TLE) (for details) and tissue from C57BL/6J mice to investigate the precise localization and expression patterns of this gene." (PMID 39739583, 2025). "Downregulating D‐2‐hydroxyglutarate dehydrogenase (D2HGDH) increases epilepsy susceptibility by altering reactive oxygen species (ROS) levels and synaptic function, contributing to oxidative stress in neurons." (PMID 39739583, 2025). "Here, it is demonstrated that downregulating D‐2‐hydroxyglutarate dehydrogenase (D2HGDH) enhances susceptibility to epilepsy." (PMID 39739583, 2025). "Behavioral observations, western blotting, immunofluorescence staining, and electrophysiological methods were used to investigate the influence of D2HGDH on epilepsy and its underlying mechanisms." (PMID 39739583, 2025). "Furthermore, the acid calcium‐independent phospholipase A2 (aiPLA2) inhibitor, MJ33, restores the GSH/GSSG balance and reverses the increase in ROS levels caused by D2HGDH knockdown, resulting in remission of epilepsy‐related behaviors." (PMID 39739583, 2025). "Recessive and rare dominant D2HGDH variants in the chiral configuration enzyme, D-2-hydroxyglutarate dehydrogenase induce D-2-hydroglutaric acid to 2-ketoglutarate, and patients present with epilepsy, hypotonia, and psychomotor retardation." (PMID 33426505, 2020). "Second, a KA‐induced epilepsy model was established to investigate the effects of upregulation or downregulation of D2HGDH on the chronic phase of seizures in KA mice using video monitoring and local field potentials (LFPs) recording." (PMID 39739583, 2025). "In this study, we identified a novel role of D2HGDH in epilepsy regarding the potential regulation of synaptic oxidative damage in neurons." (PMID 39739583, 2025). "Our data demonstrate that Prdx6 is a potential target substrate of D2HGDH in epilepsy." (PMID 39739583, 2025). "Second, we explored the potential role of D2HGDH in epilepsy models (KA and PTZ models)." (PMID 39739583, 2025). "Our results suggest that the D2HGDH/GSH/Prdx6/ROS axis may be involved in the development of epilepsy and that MJ33, an inhibitor of aiPLA2, could potentially reverse this phenotype." (PMID 39739583, 2025). "In conclusion, targeting D2HGDH downregulation in C57BL/6J mice and neurons contributes to our understanding of the pathophysiology of epilepsy." (PMID 39739583, 2025).
Ataxia (1 paper, 2023). Ataxia refers to impaired coordination of voluntary muscle movement. "In humans, mutations in D-2-hydroxyglutarate (D-2HG) dehydrogenase (D2HGDH) result in D-2HG accumulation, delayed development, seizures, and ataxia." (PMID 37043428, 2023). "In humans, mutations in D-2-hydroxyglutarate dehydrogenase (D2HGDH) cause delayed development, seizures and ataxia." (PMID 37043428, 2023).
B-cell lymphoma (1 paper, 2015). "Nonetheless, the role of D2HGDH in driving at least part of this remodelling is supported by multiple isogenic B-cell lymphoma models of loss and gain of D2HGDH function." (PMID 26178471, 2015).
D-2-hydroxyglutaric aciduria (1 paper, 2015). D-2-hydroxyglutaric aciduria (D-2-HGA) is a rare clinically variable neurological form of 2-hydroxyglutaric aciduria characterized biochemically by elevated D-2-hydroxyglutaric acid (D-2-HG) in the urine, plasma and cerebrospinal fluid. "The D2HGDH mutations described in type I D-2-hydroxyglutaric aciduria and in DLBCL are highly clustered." (PMID 26178471, 2015).
head and neck squamous cell carcinoma (1 paper, 2020). A squamous cell carcinoma that arises from any of the following anatomic sites: lip and oral cavity, nasal cavity, paranasal sinuses, pharynx, larynx, and salivary glands. "High expression of D2HGDH has also been found in head and neck squamous cell carcinoma (HNSCC), where it was reported to be a protective factor conferring low risk." (PMID 33019704, 2020).
tumor (11 papers, 2010 to 2025). "We concluded that partial loss of D2HGDH has metabolic and cellular consequences, supporting a haploinsufficiency model for tumours with heterozygous inactivating mutation of this gene." (PMID 26178471, 2015). "Using this as a rationale to explainalternate methods of 2HG production, a recent study examined secondary GBMs and otherCNS tumours for inactivating mutations of D2HGDH or L2HGDH." (PMID 21317451, 2010). "Alternatively, if 2HG accumulation is critical, some tumours might acquire somatic D2HGDH or L2HGDH mutations." (PMID 21625441, 2011). "We observed that there were statistically significant interactions between IDH tumor mutation status and CCDC26 (rs55705857), PHLDB1 (rs7125115), and D2HGDH (rs71430382) germline variants." (PMID 40709013, 2025). "Secondly, excess D-2HG accumulation alters CD8 T lymphocyte activity and D2hgdh knockdown decreased the anti-tumor activity of these cells." (PMID 40236175, 2025). "Again, tumor cell growth was dramatically suppressed by the expression of D2HGDH (Tumor size at 25 days: 343 ± 52 mm3 vs. 76 ± 22 mm3 for D2HGDH vs. Vec; p = 0.0002)." (PMID 25825982, 2015). "To address this possibility, we first investigated a panel of parental DLBCL cell lines and primary tumours expressing either mutant or WT D2HGDH." (PMID 26178471, 2015). "We confirmed the somatic nature of the D2HGDH mutations in two primary tumours, but did not have constitutive DNA to examine the other cases." (PMID 26178471, 2015). "Notably, ectopic expression of D2HGDH which partially reduces D-2-HG, does not change histone methylation markers and TET2-induced 5 hmC production in HT1080 cells, yet D2HGDH overexpression effectively inhibits the anchorage independent growth and tumor growth of these cells." (PMID 25825982, 2015). "ADH5, NUDT7, PTGES3, D2HGDH, HAO2 and CPT1C also play regulatory roles in the pathological processes of various tumours." (PMID 36643625, 2023). "However, we acknowledge that given the heterogeneity of DLBCL, one cannot exclude the possibility that additional genetic events may contribute to part of the epigenetic differences that we found in the DLBCL cell lines and primary tumours dichotomized by the D2HGDH status." (PMID 26178471, 2015). "Importantly, although some of the DLBCL cell lines and primary tumours examined harbour mutations in histone methylation regulators, the presence of these abnormalities, appears to not influence the D2HGDH-driven separation in groups of samples with high and low H3K4/K9 methylation levels." (PMID 26178471, 2015).
cancer (8 papers, 2015 to 2025). A tumor composed of atypical neoplastic, often pleomorphic cells that invade other tissues. "In this respect, an increase in L2HG has similar consequences to those caused by increases in D2HG (and a decrease in D2HGDH) observed in other types of cancers." (PMID 36133305, 2022). "Therefore, induction of D2HGDH expression may be another potential approach to treat IDH-mutated cancer." (PMID 25825982, 2015). "The Km value of D2HGDH for (D)-2-HG is 0.12 mM, implicating that this enzyme is involved in the metabolism of (D)-2-HG in mIDH1/2-carrying cancer cells." (PMID 37546420, 2023). "Our data link D2HGDH to cancer and describe an additional role for the enzyme: the regulation of IDH2 activity and α-KG-mediated epigenetic remodelling." (PMID 26178471, 2015). "D2hgdh mutations, however, are not generally associated with elevated cancer risk." (PMID 40236175, 2025). "Here, it should be noted that D-2-HGA may have a more aggressive clinical course than L-2-HGA11, 25, and as the patients succumb to their disease more rapidly, it may not be possible to determine whether deficiency of D2HGDH can also influence the long-term susceptibility to cancer." (PMID 26178471, 2015). "Inhibition of the production of D2HG production by IDH1 mutation inhibitor ivosidenib or catabolism of D2HG by overexpression of D2HGDH may reverse D2HG induced muscle proteolysis and slow the progression of cancer cechexia." (PMID 37741882, 2023).
neurologic disease (1 paper, 2015). "It is certain, nonetheless, that cellular accumulation of D2-HG is toxic, as evidenced by the extensive neurologic disease and rapid clinical deterioration of infants with bi-allelic loss of D2HGDH." (PMID 26178471, 2015).
D2HGDH also shares sentences with these, for which no sentence is quoted: glioblastoma (3 papers); allergic disease (2); eczema (2); Airway obstruction (1); allergies (1); anaphylaxis (1); astrocytoma (1); behavioral disorders (1); brachydactyly (1); breast tumors (1); colitis (1); dermatitis (1); genetic diseases (1); L2-hydroxyglutaric aciduria (1); lymphoma (1); motor neuron degeneration (1); myeloid leukemia (1); oligoastrocytoma (1); oligodendroglioma (1); prostate carcinoma (1); respiratory disease (1); rheumatoid arthritis (1); Seizure (1); temporal lobe epilepsy (1).